RN7SL643P (RNA, 7SL, cytoplasmic 643, pseudogene)
Gene: Miscellaneous RNA gene on chromosome 6 (86,435,848 to 86,436,138, forward strand). Ensembl gene ENSG00000243124.
Homologues: Orthologues: chimpanzee Metazoa_SRP (99% identical), macaque Metazoa_SRP (87% identical). Paralogues in human: RN7SL2 (83% identical), RN7SL1 (83% identical), RN7SL3 (81% identical), RN7SL45P (79% identical), RN7SL186P (79% identical), RN7SL50P (79% identical), RN7SL679P (79% identical), RN7SL386P (78% identical), RN7SL589P (78% identical), RN7SL655P (78% identical), RN7SL300P (78% identical), RN7SL492P (78% identical), and 700 more.